IL7 (interleukin 7)
Diseases named in the same sentence as IL7 in open-access papers (continued):
Sharing a sentence is not in itself a finding about the gene and the disease.
Sepsis (continued). "Also, IL-7 levels in sepsis were significantly lower compared to the malaria and febrile control groups." (PMID 35811678, 2022). "Notably, IL-7 replacement therapy was recently studied in a Phase IIb trial among adults with sepsis." (PMID 35185860, 2021). "Since the number and function of CD4+T and CD8+T cells decrease in elderly patients with sepsis, while Tregs increase in frequency and suppressive function in both aging and septic patients, IL-7 administration could a possible treatment strategy." (PMID 33532141, 2021). "The success of the IL-7 clinical trial shed some light on the management of sepsis." (PMID 32983116, 2020). "It is inspiring that IL-7, a growth factor that stimulates the proliferation and maturation of many cell types, could continuously boost the absolute T lymphocyte counts of sepsis patients in a phase II clinical trial." (PMID 33132754, 2020). "As IL-7 has been shown to efficiently restore sepsis-induced T-cell proliferation in ex vivo T cells of patients with sepsis and in murine models of sepsis, we tested IL-7 efficacy in restoring a functional status in the current model of TCR activation of T cells from HVs." (PMID 30995946, 2019). "An important feature of immunosuppression is T cell exhaustion, which was recently recognized following many trials for sepsis involving immunoregulatory therapies, such as PD-1 blockade, interleukin 7 administration, interleukin 15 administration, IFN-γ administration, and CTLA-4 blockade." (PMID 31440257, 2019). "The overall absence of membrane IL-7R regulation in patients strengthens the use of IL-7 in septic shock and is consistent with preliminary data in preclinical models of sepsis which showed the efficacy of this molecule in restoring sepsis-induced T-cell alterations." (PMID 30995946, 2019). "IL-7 treatment from d5-9 resulted in significantly higher spleen cell numbers as compared with non-treated septic mice only at the very late time point (d113) after sepsis induction." (PMID 30730978, 2019). "Finally, we showed that IL-7 improved T-cell proliferation in our model, as observed ex vivo with T cells from patients with sepsis." (PMID 30995946, 2019). "Interestingly, 1 month post-sepsis both the frequency and the numbers of IL-10+ B cells were higher in IL-7-treated septic mice than in sham mice and remained elevated even 3.5 months after sepsis induction." (PMID 29466409, 2018). "The first “proof of concept” clinical trials on IL-7 during sepsis are conducted in USA and Europe." (PMID 29977234, 2018). "Sepsis induced an increase in IL-10+ B cells, which was enhanced and prolonged by IL-7 treatment." (PMID 29466409, 2018). "The administration of exogenous cytokines can have a marked effect on the number and function of various immune cell populations in sepsis survivors, as demonstrated by the preclinical and clinical data touting the benefits of IL-2, IL-7, IL-15, and Flt3L (among others)." (PMID 30379932, 2018). "Interestingly, even at the very late time point of 3.5 months after sepsis induction, the frequency of the Gr1+CD11b+ population in the bone marrow of septic and IL-7-treated septic mice remained higher than the sham mice." (PMID 29466409, 2018). "Studies of PGx of ACE inhibitors in cardiovascular disease and IL-7 in cancer could inform angiotensin II and IL-7 PGx in sepsis." (PMID 27384443, 2016). "Several such immune modulators are being advocated as potential treatments for sepsis, including cytokines (interleukin 7, interleukin 15, GM-CSF, interferon γ) and co-inhibitory molecular blockade (eg, anti-programmed cell death receptor-1 and anti-B and T lymphocyte attenuator)." (PMID 26917434, 2016). "IL-7 gene expression was similar in controls and bacteraemia, but lower in sepsis (P < 0.0001)." (PMID 21711552, 2011).
Sepsis (continued). "While IL-7 may have the potential to reverse sepsis induced apoptosis and rhIL-2 related apoptosis in PBL of septic patients, this will require further investigation and is beyond the scope of the current project." (PMID 21711552, 2011). "In cultured PBLs, IFN-γ gene expression was decreased in response to LPS and increased in response to CD3ab with sepsis: IL-7 gene expression increased in response to LPS in controls and to CD3ab with sepsis; Bcl-2 gene expression decreased in response to combined CD3ab and IL-2 with sepsis." (PMID 21711552, 2011). "IL-2 gene expression was lower in bacteraemia patients compared with controls, and lower still in patients with sepsis; IL-7 gene expression was similar in control and bacteraemic patients, but lower in patients with sepsis; IL-15 gene expression was similar in the three groups." (PMID 21711552, 2011). "This included traditionally evaluated cytokines (IL-1β, IL-6, IL-8, IL-10 and TNF-α) and a number of cytokines that are not commonly associated with sepsis (IL-7, IL-13, IFN-γ and MCP-1)." (PMID 17448250, 2007). "Our study revealed that the median IL-7 values of all the patient groups studied exceeded the established cut-off value, so endogenous IL-7 levels might be a valuable tool for immunomodulatory therapy in sepsis." (PMID 40005375, 2025). "Endogenous IL-7 levels may represent a potential prognostic indicator in sepsis." (PMID 41158471, 2025). "Similarly, pediatric sepsis survivors often have higher IL-7 levels compared to healthy children." (PMID 41158471, 2025). "Additionally, immune dysfunction in sepsis may impair the clearance of IL-7, thereby contributing to its sustained levels." (PMID 41158471, 2025). "These insights may inform new therapeutic targets for treating immune impairment in sepsis, including the use of IL-7 or IFN- γ therapy or PD-1 targeting antibodies, which have been shown to reverse T cell dysfunction in murine models of sepsis and a small number of human case studies." (PMID 41208955, 2025). "Artificial intelligence-driven multi-omics methods, including genomics, microbiome profiling, and radiomics, could facilitate the stratification of patients with sepsis according to IL-7/IL-7R mRNA variability, microbial ecology, or metabolic–epigenetic states." (PMID 41158471, 2025). "This work team with the corresponding author named Didier Payen found that taking advantage of interleukin (IL)-7, an immune-mediated modulator in anti-programmed cell death, might be the future in the treatment of sepsis, evidenced by the suppression of cytokine as well as the exhaustion of T cell." (PMID 36211966, 2022). "With regard to recombinant cytokines, IL-7 especially is attractive considering its ability to affect many different immune effector cells implicated in pathogen elimination (e.g., CD4 and CD8 T cells, and innate lymphoid cells) and to improve outcome in experimental sepsis." (PMID 36470832, 2022). "Therefore, IL-7 treatment is beneficial for promoting T-cell proliferation in patients with sepsis." (PMID 36209190, 2022). "Moreover, there was a massive increase in CD3+CD8+ T cells after sepsis in the IL-7 treated mice." (PMID 30730978, 2019). "Interestingly, however, 1 week post sepsis, both the relative frequency and the absolute number of Tregs were significantly higher in IL-7-treated septic mice than in untreated septic mice or control mice, indicating a preferential survival of Tregs over effector T cells upon IL-7 administration." (PMID 29466409, 2018). "With the presented results in this study, demonstrating that LPS-activated tolerant CD14+ monocytes upregulate IL7R on the cell surface, it can be speculated that IL-7 administration during sepsis will also affect the IL7R-positive tolerant monocyte population." (PMID 28404994, 2017).
Sepsis (continued). "Over the first week of illness, patients with sepsis upregulate the expression of a number of important inhibitory receptors and their ligands on the surface of lymphocytes and dendritic cells, downregulate expression of the receptor for IL-7 and increase the numbers of Treg cells." (PMID 22742734, 2012). "IL-7’s effect on upregulating VLA-4 has been previously reported in vitro, and peripheral administration of recombinant human IL-7 (rhIL-7) has been observed to increase VLA-4 and T cell trafficking in murine models of sepsis." (PMID 40244705, 2025). "A recent clinical trial demonstrated that IL-7 therapy successfully restored depleted CD4+ and CD8+ effector cells by threefold to fourfold in patients with sepsis." (PMID 39720718, 2024). "Interventional studies have shed light on the therapeutic potential of IL-7, the ligand for CD127, in reversing sepsis-induced lymphocytopenia." (PMID 38601150, 2024). "Hepatocyte growth factor (HGF), IL-7, IL-15, IL-22, Ac2-26, Vaspin, Hsp22, and adiponectin (APN) exhibit anti-apoptotic functions in the prevention and treatment of sepsis." (PMID 37629199, 2023). "IL-7 is noted to increase CD4+ and CD8+ T cell numbers in murine sepsis by upregulating the expression of the anti-apoptosis regulator B-cell lymphoma 2 protein, which is associated with improved survival." (PMID 33920518, 2021). "IL-7 has been used as immunotherapy in pre-clinical and clinical studies to treat cancer, HIV infection and sepsis." (PMID 34603318, 2021). "While IL-2, CXCL10, and TNF-α contribute to the pathogenesis of sepsis, IL-7, IL-10, GCSF, MCP1, M1P1A are likely elevated as an endogenous attempt to combat sepsis." (PMID 32973504, 2020). "Immediately after sepsis, at day 8 after PCI, the number of CD8+ T cells was significantly higher in the IL-7 treated septic mice than in the two other groups." (PMID 30730978, 2019). "Comparison of molecules between the control and sepsis groups revealed statistically significant differences, except for IFN-α, IL-1RA, IL-1β, IL-2, IL-6, IL-7, IL-15, LIF, GM-CSF, TNF-α, CCL4, CCL5, and CXCL12." (PMID 31583025, 2019). "A small phase II clinical trial of IL-7 was recently conducted in patients with septic shock, some of whom had MDR bacterial infection in the context of sepsis." (PMID 29944697, 2018). "This cytokine gene expression index consisted of the difference in log mRNA copy numbers for cytokines that were decreased in sepsis, namely, IFNγ, TNFα, IL7, and IL23, and the cytokine increased in sepsis, namely, IL10 (IFNγ + TNFα + IL7 + IL23–IL10)." (PMID 23935244, 2013). "An algorithm utilising mRNA copy number for TNFα, IFNγ, IL7, IL10, and IL23 accurately distinguished sepsis from severe sepsis with a receiver operator characteristic value of 0.88." (PMID 23935244, 2013). "When patients with infection and patients with severe sepsis on ICU admission were compared, IL2, IL7, IL23, IFNγ, and TNFα gene expression was lower in patients with sepsis, while IL-27 gene expression was similar in these two groups." (PMID 23935244, 2013). "Concentrations of IL-1β, IL-6, IL-7, IL-8, IL-10, IL-13, interferon-γ, MCP-1 and tumour necrosis factor-α were significantly higher in septic shock patients than in those with severe sepsis." (PMID 17448250, 2007). "One study revealed a change in serum IL-7 between sepsis survivors and non-survivors, but it cannot be regarded as a mortality marker." (PMID 41158471, 2025). "In summary, endogenous IL-7 and IL-7R levels can be elevated in sepsis; however, this does not reverse the dysfunction and depletion of immune cells, even when accompanied by other decompensatory changes." (PMID 41158471, 2025). "Based on the ROC curve analysis of IL-7, the cutoff value for IL-7 was determined to be 1.94 pg/mL with a sensitivity of 74.23% and a specificity of 75.34% for diagnosing sepsis or septic shock, irrespective of mortality status." (PMID 40005375, 2025).
Sepsis (continued). "In any case, recombinant IL-7, a growth factor for progenitor lymphoid cells, might be tried to rescue relapsing VL patients with AIDS as has been tried for patients with sepsis." (PMID 38921748, 2024). "Immunoadjuvant adjunctive IFN-γ therapy, along with IL-7 and anti-PD1/PD-L1, could be beneficial for patients with sepsis, as it has proven impacts on enhancing CD4+ and CD8+ T cell functions." (PMID 39720718, 2024). "Previously, we reported a non-statistically significant trend (p = 0.07) for IL-7 to increase monocyte HLA-DR expression in patients with sepsis who were treated with CYT-107 versus placebo." (PMID 36906875, 2023). "Despite triggering rapid proliferation of 1° TCIRCM cells, administration of IL-7 did not boost the numerical restoration of 4° TCIRCM cells which further capitalizes the accumulation of 1° TCIRCM cells after sepsis." (PMID 36756117, 2023). "In 2018, the phase 2b clinical trial studying the ability of recombinant human IL-7 to reverse the immunosuppression in sepsis demonstrated that the IL-7 treatment increased the number of lymphocytes without exacerbating inflammation." (PMID 33679715, 2020). "Therefore, the disruption of IL-7/IL-7R signalling during confirmed LOS has potentially detrimental implications for regulation of immune and cellular homeostasis that contributes to sepsis pathophysiology." (PMID 32479514, 2020). "Although CD4+ and CD8+ T cells express the IL-7R at similar levels, we found that the beneficial effect of IL-7 treatment on T cell recovery was more pronounced for CD8+ T cells than for CD4+ T cells, which confirms and extends earlier reports on other sepsis models." (PMID 30730978, 2019). "We therefore studied the long-term recovery of different T cell subsets after sepsis with or without IL-7 treatment in the model of peritoneal contamination and infection (PCI)." (PMID 30730978, 2019). "Whereas numerical recovery of T lymphocytes occurred quickly after sepsis and was accelerated by IL-7 treatment, the Th cell response against a fungal antigen was impaired 1 month after sepsis, regardless of IL-7 treatment." (PMID 30730978, 2019). "We have used the mouse model of peritoneal contamination and infection (PCI) to investigate the quantitative and qualitative recovery of T lymphocytes for 3.5 months after sepsis with or without IL-7 treatment." (PMID 30730978, 2019). "The percentage and number of CD3+CD4-CD8-T lymphocytes was strongly increased in sepsis-surviving mice at day 8 after PCI with or without IL-7 treatment." (PMID 30730978, 2019). "Given the well-documented critical function of IL-7 for lymphocyte homeostasis, our findings do not indicate any sepsis-specific effect of IL-7 but rather reflect the physiological functions of IL-7 which also occur in the setting of sepsis." (PMID 29466409, 2018). "The aim of this study was to evaluate the numbers and frequencies of immunoregulatory cell populations for 3.5 months after sepsis induction in the presence or absence of early IL-7 treatment." (PMID 29466409, 2018). "The present results showing a potent effect of IL-7, OX-40L, and anti-PD-L1 to improve T cell IFN-γ production in patients with MDR bacteria provides additional support for clinical trials of these agents in life-threatening sepsis due to MDR bacteria." (PMID 29944697, 2018). "Interestingly, IL-7 treatment resulted in an immediate increase in the classical Foxp3+CD25+ Treg population, 1 week after sepsis induction." (PMID 29466409, 2018). "We have used the mouse model of peritoneal contamination and infection (PCI) to investigate the expansion of immunoregulatory cells as long-term sequelae of sepsis with or without IL-7 treatment." (PMID 29466409, 2018). "Unlike IL-7, IL-15 is a potent promoter of NK cell and DC functions, which can be defective in sepsis." (PMID 26322041, 2015).
Sepsis (continued). "Furthermore, IL-7 can mediate the crosstalk between TH1 and TH17 lymphocytes during sepsis such that neutrophil recruitment and bacterial clearance are improved." (PMID 25302303, 2014). "In this study it was notable that decreased IL7 gene expression characterised severe sepsis rather than infection." (PMID 23935244, 2013). "We compared cytokine concentrations among patients with severe sepsis and septic shock, and observed that concentrations of IL-1β, IL-6, IL-7, IL-8, IL-10, IL-13, IFN-α, MCP-1 and TNF-α were significantly increased in septic shock as compared with severe sepsis." (PMID 17448250, 2007). "Exogenous IL-7 can enhance immune function, regulate inflammation, and exert anti-apoptotic effects, but it does not reduce sepsis-related mortality, suggesting that its therapeutic potential may require combination with other interventions." (PMID 41158471, 2025). "Immunomodulatory cytokines (IFN-γ, IL-7, -15, -33), growth factors (GM-CSF), thymosin-α, immune checkpoint inhibitors (PD-1/PD-1L, CTLA-4, LAG-3, TIM-1), administration of immunoglobulins, and cell therapy with mesenchymal cells are being studied for use in patients with sepsis." (PMID 40566028, 2025). "In sepsis, the regulation of IL-7 is complex and has not been thoroughly investigated." (PMID 40005375, 2025). "Moreover, the lack of a comprehensive biochemical model for IL-7 synthesis and dynamics in sepsis and septic shock further complicates the interpretation of these results." (PMID 40005375, 2025). "Exogenous IL-7 may modulate immune function in patients with clinical sepsis but does not reduce mortality." (PMID 41158471, 2025). "Given the intricate and variable nature of sepsis, depending solely on IL-7 or IL-7R may not adequately reflect the disease’s multifactorial nature." (PMID 41158471, 2025). "This suggests that, while IL-7 may enhance immune function, it does not address the broader pathophysiology of sepsis." (PMID 41158471, 2025). "More specifically, IL-7, IL-15, granulocyte-macrophage colony stimulating factor (GM-CSF), anti-programmed cell death receptor-1 (PD-1), and anti- B- and T-lymphocyte attenuator (BTLA) targeted the immunosuppressive status of critically patients with sepsis shock." (PMID 36439140, 2022). "The results showed that IL-7 treatment does not cause excessive inflammatory reactions or aggravate organ dysfunction but significantly increases CD4+ and CD8+ T lymphocyte counts in patients with sepsis." (PMID 36209190, 2022). "A novel virotherapy based on the non-propagative Modified Virus Ankara (MVA) expressing the human interleukin-7 (hIL-7) cytokine fused to an Fc fragment, MVA-hIL-7-Fc, was developed and shown to enhance innate and adaptive immunity and confer survival advantages in murine sepsis models." (PMID 36045686, 2022). "A principal component analysis and a receiver operator characteristic curve analysis, identified seven potential biomarkers; IL-1β, IL-7, IL-12, IL-1RA, RANTES/CCL5, MIP1β/CCL4 and IP10/CXCL10 that could discriminate children with sepsis from clinical malaria and other febrile conditions." (PMID 35811678, 2022). "Additionally, using an ROC curve analysis, the plasma levels of IL-1β, IL-7, IL-12, IL-1RA, RANTES/CCL5, MIP1B/CCL4 and IP10/CXCL10 could help differentiate children with sepsis from both clinical malaria and febrile controls." (PMID 35811678, 2022). "In addition, IL-7 treatment has been reported to reduce T cell apoptosis, restore IFN-γ production, facilitate pathogen clearance, and improve survival in mouse models of sepsis." (PMID 33532141, 2021). "In addition, mice were randomly allocated to the IL-7 treatment group, which was treated subcutaneously with 2.5 μg recombinant human IL-7 daily from d5–9 post sepsis induction, or the control group, which received no further treatment." (PMID 30730978, 2019).